TNC (tenascin C)
Diseases named in the same sentence as TNC in open-access papers (continued):
Sharing a sentence is not in itself a finding about the gene and the disease.
melanoma (31 papers, 2008 to 2025). A malignant, usually aggressive tumor composed of atypical, neoplastic melanocytes. "A growing body of evidence has implicated the role of the TNC gene in the process of invasion and metastasis for melanoma." (PMID 35806253, 2022). "TNC protein is a multifunctional matricellular glycoprotein, which is highly expressed in most melanoma cell lines, and it has been implicated in the progression of melanoma." (PMID 35806253, 2022). "Increased production of ECM proteins, such as gamma 2 chain of laminin 5 (laminin 5 γ2), hyaluronan, collagen I, biglycan, tenascin-C and fibronectin are associated with melanoma progression." (PMID 34067929, 2021). "A comparison with four otherCNS malignancies (brain metastasisfrom NSCLC and melanoma, medulloblastoma and meningioma) revealedthat plasma levels of TNC+ EVs were most elevated in theglioblastoma patients." (PMID 40056466, 2025). "While comparing our DEPs in nevi with those in corresponding NAMs, which serve as indicators of melanoma progression from premalignant lesions, we identified that TNC was upregulated in 1 of 16 matched top 25 DEPs." (PMID 41271007, 2025). "•Proteins linked to melanoma development (PRG4, APOC4, SERPIND1, VWF, TNC and PLG) were identified in the plasma-derived EVs of patients with melanoma." (PMID 39405606, 2024). "Proteins (APOC4, PRG4, PLG, TNC, VWF and SERPIND1) and metabolites (lyso PC a C18:2, PC ae C44:3) previously associated with melanoma pathogenesis were identified as relevant in differentiating between disease stages." (PMID 39405606, 2024). "Among the ECM components enhanced in melanoma is tenascin C (TNC), which mediates melanoma growth and metastatic spread." (PMID 35558554, 2022). "Regarding melanoma, tenascin C and fibronectin affect the organization of collagen fibers and biglycan is involved in matrix contraction and increased matrix stiffness." (PMID 32984031, 2020). "Despite the abundance of collagen I, melanoma progression is characterized by the increase of other matrix proteins such as tenascin-C and fibronectin." (PMID 32984031, 2020). "Elevated tenascin C level is also frequently found in human melanomas, where this protein supports malignant melanocyte survival, invasion, and metastasis." (PMID 31717496, 2019). "The only other known ECM-related transcript consistently upregulated at the RNA level was TNC (Tenascin-C), which has been shown to be involved in melanoma progression." (PMID 26944546, 2016). "These include known melanoma-promoting proteins such as fibronectin and tenascin C, but also novel promising candidates such as BAMBI, a negative regulator of TGF-beta signaling." (PMID 27689402, 2016). "In this study, we observed an increase in Tenascin-C biogenesis in melanoma cells expressing reduced level of fibronectin, suggesting a compensatory mechanism in response to drug treatment." (PMID 26944546, 2016). "We analyzed the expression of tenascin-W and tenascin-C by immunoblotting and by immunohistochemistry on multiple frozen tissue microarrays of carcinomas of the pancreas, kidney and lung as well as melanomas and compared them to healthy tissues." (PMID 22947174, 2012). "Recently, the expression of TNC was found to be elevated in advanced melanomas and in the stem cell-like side populations of the melanoma spheres, suggestive of a role in cancer stem cells." (PMID 22481923, 2012). "In fact, we observed an increase in Tenascin-C biogenesis by shFN melanoma cells." (PMID 26944546, 2016). "It is reported that tenascin-C is highly expressed in melanoma cells." (PMID 25671570, 2015). "Moreover, TNC is reported as a critical regulator of melanoma progression." (PMID 41271007, 2025). "Our results revealed for the first time that silencing the OPN gene influences proliferation and invasion of melanoma cells by effecting EGFR, tenascin C, survivin, galectin-3 and enolase 2 expression." (PMID 34257527, 2021).
melanoma (continued). "All others demonstrate an increased expression in melanoma development, some even strongly like PMP2 (5.7-fold), TNC (10.2-fold), MMP1 (65.6-fold), and CDH2 (10.2-fold)." (PMID 34439267, 2021). "Knockdown of tenascin-C elicited a dramatic decrease of the ABCB5-positive side population of melanoma cells, and markedly increased the sensitivity of melanoma cells to doxorubicin." (PMID 29156643, 2017). "Our study also revealed that DPG could increase miR-4443 and miR-3620 expression in melanoma cells, which are predicted to target the NF-kB post-transcriptional genes, CD209 and TNC, respectively." (PMID 35806253, 2022). "Similarly, increased expression of key proteins in melanoma diagnosis and malignancy is elevated in both MeLiM melanomas and human melanomas, such as S100, RACK1, and tenascin C." (PMID 32652526, 2020). "More than a three-fold increase of tenascin C mRNA in MeLiM melanoma tissue compared to contralateral normal skin was observed, accompanied by elevated protein level." (PMID 31717496, 2019). "Whereas the role of TNC (tenascin C) and FN1 (fibronectin 1) in melanoma development is well documented, implication of MARCKS, RCN3, BAMBI, PEA3/ETV4 and the FK506 family members FKBP7, FKBP10 and FKBP11 in melanoma progression is unclear." (PMID 27689402, 2016). "Furthermore, βig-H3 observed at the invasion front of melanomas co-localized with fibrillar fibronectin/tenascin-C/periostin structures, suggesting an important role for βig-H3 in ECM deposition and invasive growth of melanoma cells." (PMID 22949874, 2012). "•Melanoma-negative sentinel lymph node carries more contents of the sEV cargoes, CD38, LGALS9 (galectin-9), and TNC (tenascin-C), in the lymphatic sinuses compared with control lymph nodes." (PMID 41271007, 2025). "Among the upregulated candidates in plasma-derived EVs were melanoma markers, such as MCAM, TNC, and TGFBI, which were not regulated in depleted plasma samples." (PMID 38353833, 2024). "Furthermore, known melanoma markers, such as MCAM, TNC, and TGFBI, were upregulated in melanoma EVs but not in depleted melanoma plasma, highlighting the specific information contained in EVs." (PMID 38353833, 2024).
lung carcinoma (25 papers, 1998 to 2025). "Among the targeted lung‐cancer‐associated sEV makers (i.e., THSB2, VCAN, and TNC), we selected TNC for sEV capture because it was consistently expressed across the tested lung cancer cell lines used in this study." (PMID 36394090, 2022). "TNC was associated with breast and lung cancer and was over-expressed in vulvar intraepithelial neoplasia." (PMID 16893473, 2006). "TNC is also increased in lung cancer and the expression of TNC, S100A10, and S100A11 can predict survival in patients with lung adenocarcinoma." (PMID 36829478, 2023). "TNC has been identified as a promoter of both lung cancer progression and pulmonary metastasis formation." (PMID 36865293, 2023). "TFC and TNC can effectively suppress the growth of lung cancer cells in vitro, ex vivo and in vivo by targeting EGFR/VEGFR-Akt/NF-κB pathways." (PMID 25138052, 2014). "Nevertheless, increased TNC is present in lung cancer patients, and gene and protein interaction analysis showed that TNC interacts with ECM and inflammatory proteins, which warrants further investigation into their roles in the development and progression of lung cancer." (PMID 36829478, 2023). "Furthermore, the overexpression of TNC can promote the spread of lung adenocarcinoma cells in a genetically modified mouse model of lung cancer." (PMID 36829478, 2023). "Furthermore, overexpression of TNC (through CRISPR/Cas9 technology) confirmed a metastasis-driving role of TNC in a human lung carcinoma grafting model." (PMID 36102918, 2022). "Tenascin-C is also proteolytically cleaved by MMP-2 and cathepsin B, and degradation was associated with higher recurrence and a worse prognosis for the patients with lung cancer." (PMID 35008401, 2022). "Our study has suggested that TFC and TNC may have the therapeutic and/or adjuvant therapeutic applications in the treatment of lung cancers and other cancer." (PMID 25138052, 2014). "All these findings suggest that TFC and TNC as novel anticancer compounds may have the therapeutic and/or adjuvant therapeutic applications in the treatment of lung cancer and other cancers." (PMID 25138052, 2014). "In order to further confirm the inhibitory effects of TFC and TNC on the signaling pathways related to the migration and growth of the lung cancer cells, we investigated the effects of TFC and TNC on the suppression of the phosphorylation and/or expressions of Akt and NF-κB in LLC cells." (PMID 25138052, 2014). "As anti‐TNC antibody‐functionalized nanopillars enrich cancer‐associated sEVs, we expected DECODE to provide an sEV molecular profile with higher expressions of CD63, THBS2, VCAN, and TNC in the three lung cancer cell lines and low/negligible biomarker expression from HBECs and PBS controls." (PMID 36394090, 2022). "Neuron-glial 2 (NG2, also known as CPSG4), an angiogenic pericyte protein associated with the pre-metastatic niche, and tenascin-C, an extracellular matrix protein frequently overexpressed in lung cancer, were not greatly affected by environment transfer in either hMSC or tumor stromal cells." (PMID 30862796, 2019). "Furthermore, they discovered that there was a correlation between in vivo TNC expression and fibrin accumulation in head and neck squamous cell carcinomas (SCC) and lung carcinomas, further confirming that TNC functions as a regulator of the fibrinolytic system." (PMID 31106200, 2019). "Suppression of these receptors-activated Akt-NF-κB signaling pathways by TFC and TNC could greatly contribute to the inhibition of the migration and growth of lung cancer LLC and A549 cells as well as the LLC and A549 tumor growth in tumor-bearing mice as we observed in the present study." (PMID 25138052, 2014). "Compared with those in PC9 lung cancer cells, the mRNA expression of PLAT, ITGB3, TNC, AKT, FAK and PI3K were upregulated in PC9GR." (PMID 39754146, 2025). "Higher levels of Tenascin C (TNC), ICAM1, and VEGFA further supported that they were involved in pleural metastasis in lung cancer." (PMID 37649596, 2023).
lung carcinoma (continued). "However, whether TNC plays a role in other types of lung cancer is unknown." (PMID 36829478, 2023). "The levels of Tenascin C and VEGFA were higher in the MPE of EGFR-mutated lung cancer patients but not Fibronectin, ICAM-1, nor PAI-1." (PMID 37649596, 2023). "To understand the molecular mechanisms by which TFC and TNC inhibit cell growth and induce apoptosis in lung cancer cells, we studied the effects of TFC and TNC on the expressions of proteins related to cell growth and apoptosis as well as cell cycle arrest in LLC cells." (PMID 25138052, 2014).
brain tumor (22 papers, 2012 to 2025). "In particular, collagen type 6 family, fibronectin, and tenascin C, which are rarely expressed in normal areas, exhibited prominent expression in the brain tumor tissue." (PMID 38675489, 2024). "Brain tumor CSCs express the exosomal markers TSG 101 (tumor susceptibility gene) and flotillin 1 which can suppress T-cell activity by the upregulation of tenascin-C." (PMID 35163368, 2022). "It has also been reported that TNC is a promoter of the invasiveness of brain tumor-initiating cells through a mechanism involving ADAM-9 proteolysis via the c-Jun NH2-terminal kinase pathway." (PMID 35968275, 2022). "Brain tumor CSCs were found to express the exosomal markers tumor susceptibility gene (TSG) 101 and flotillin 1, as well as upregulating tenascin-C, resulting in suppressed T cell activity." (PMID 34062950, 2021). "Analysis of brain tumor CSCs showed an exosomal release of tenascin-C, which inhibited T cell activation and proliferation." (PMID 34062950, 2021). "Tenascin-C expression was successfully targeted in aggressive brain tumors with a double stranded RNA homologous to tenascin-C triggering its degradation." (PMID 31032255, 2019). "They suggested that the chimeric antibody of TNC, which showed high accumulation in brain tumors, could be used as a therapeutic drug." (PMID 28106752, 2017). "Another recent study identified that ADAM9, through potentially regulating the activity of tenascin-C protein, might stimulate the invasiveness of brain tumor-initiating cells." (PMID 27571068, 2016). "In brain tumors, SMOC1 interacts with tenascin-C, an extracellular matrix protein overexpressed in various tumor types." (PMID 38429655, 2024). "Increased TNC protein expression was detected in paired post-mortem tumor tissue specimens from children with DIPG, relative to normal brain tumor specimens (n = 8, p = 0.008, Paired t-test)." (PMID 31092287, 2019). "Within primary brain tumors, components such as vitronectin, osteopontin, tenascin-C, SPARC and BEHAB can be found, and some of them are upregulated and modulate brain tumor growth, proliferation and invasion." (PMID 22973309, 2012).
colorectal cancer (22 papers, 2010 to 2025). A primary or metastatic malignant neoplasm that affects the colon or rectum. "A switch from the small or truncated form of TNC, which lacks exons 10 to 16, to predominant expression of the large, full-length variant of TNC has been demonstrated in breast, lung and colorectal carcinoma." (PMID 20678196, 2010). "Altered expression of ECM proteins, e.g. the proteoglycan tenascin C (TNC), could be correlated to cancer among a wide variety of tumor entities, including colorectal carcinoma, underlining the importance of the extracellular matrix signatures in cancer." (PMID 33099724, 2020). "Increased expression of tenascin-C has been detected in several types of benign and malignant neoplasms, and is found to associate to the invasive and metastatic potential of malignant tumors, for example esophageal squamous cell carcinoma and colorectal cancer." (PMID 28978001, 2017). "Accordingly, we used the phage-display nanobody library “B” raised against ECM of colorectal cancer metastases to the liver, to pan against full-length human TNC protein using methods described previously." (PMID 37098922, 2023). "Other studies showed that reduced DAG1 protein expression is associated with poor outcome of colorectal cancer; downregulation of FN1 decreases proliferation, migration, and invasion of colorectal cancer cells, while TNC induces EMT and proliferation." (PMID 34938324, 2021). "Tenascin-C, a matricellular protein, is highly expressed in inflammatory bowel diseases, especially colorectal cancer." (PMID 31195598, 2019). "In colorectal cancer myofibroblasts in stroma of invasive tumor front secrete tenascin-C and stimulate cancer cell invasion." (PMID 28978001, 2017). "Our studies not only shed light on the mechanism by which stromal proteins contributed to colorectal carcinogenesis, but also identified Tenascin-C as a potential stromal biomarker for colorectal cancer metastasis." (PMID 27191989, 2016). "In colorectal cancer, the frequency of Tenascin-C expression in immature stroma is high, and Tenascin-C expression represents the components of extracellular matrix produced mainly by myofibroblasts at the edge of tumor invasion." (PMID 26731558, 2016). "However, the studies on other types of cancer such as breast, brain, and colorectal cancer, did provide remarkable insight into the function of TNC on cancer growth." (PMID 36289644, 2022). "Both S100A9 and TNC levels have the potential identify colorectal cancer." (PMID 31632476, 2019). "Furthermore, a high expression of TNC is considered to be a poor prognostic factor in colorectal cancer tissues." (PMID 31195598, 2019). "In addition, our study identified an extracellular protein, Tenascin-C, as a potential stromal biomarker for colorectal carcinoma metastasis." (PMID 27191989, 2016). "Like MMP7, Tenascin-C, another Wnt target gene, is also upregulated in the normal mucosa of Bcat mice, and this persists in the tumors of these mice and in human colorectal cancer samples (n=31)." (PMID 26398937, 2015). "Our results suggested that TNC might play an important role in colorectal carcinoma metastasis." (PMID 27191989, 2016). "However, the roles of TNC in colorectal cancer (CRC) cells remain unclear." (PMID 32322169, 2020). "In general, as early diagnosis biomarkers of colorectal cancer, S100A9 and TNC levels are comprehensive." (PMID 31632476, 2019). "Tenascin-C, a large extracellular matrix hexabracchion glycoprotein, is highly expressed in the microenvironment of most solid tumors, including colorectal cancers, but is absent or greatly reduced in most adult tissues." (PMID 23145140, 2012).